PIK3CA (phosphatidylinositol-4,5-bisphosphate 3-kinase catalytic subunit alpha)
Diseases named in the same sentence as PIK3CA in open-access papers (continued):
Sharing a sentence is not in itself a finding about the gene and the disease.
cancer (continued). "Furthermore, several studies have shown the association of PIK3CA mutations with the subsequent AKT activation status and have observed the modulation of AKT activity by chemotherapeutic agents and other cancer therapeutics." (PMID 29100327, 2017). "Visual inspection of the data, however, suggested that mutations reported to occur frequently in particular cancers showed large inter‐individual variability in the ACB‐PCR MFs in normal tissues (e.g., PIK3CA H1047R for breast, KRAS G12D for colon) [COSMIC, 2016]." (PMID 28755461, 2017). "Furthermore, the SNVs in CTNNB1, PIK3CA, PTEN and ESR1 were annotated in COSMIC, the catalogue of somatic mutations in cancer." (PMID 28103826, 2017). "Further therapeutic development of Rac inhibitors for HER2+ and PIK3CA-mutant cancers is warranted." (PMID 28423521, 2017). "It is possible that deregulation of centrosome biology by oncogenic Pik3ca in a complex genetic background, as in cancer, might increase the frequency of chromosome segregation errors in cells." (PMID 29170395, 2017). "Previous studies have investigated associations between genetic variations in PTEN/PI3K/AKT signaling pathway and cancer risk, however, the association between PTEN rs701848, PIK3CA rs2699887, and AKT1 rs2494752 polymorphisms and sporadic BC in Chinese population has not been investigated yet." (PMID 28423632, 2017). "The present study also indicates that FOXO3a might be responsible for the resistance to BKM120 via induction of autophagy in PIK3CA-mutant cancer cells." (PMID 28036259, 2017). "The remarkable prevalence of PIK3CA and KRAS mutations in DNA from normal tissues suggests that there may be significant opportunities for cancer prevention." (PMID 28755461, 2017). "In the future, these findings may lead to the development of more effective therapies for human cancers in which PIK3CA is over-active." (PMID 28561737, 2017). "Therefore, researchers have been looking for other drugs that, when combined with the PIK3CA-inhibiting drug, are able to kill the cancer cells." (PMID 28561737, 2017). "In PIK3CA mutant cancer cell lines and in human breast tumors, PDK1 may activate an alternative signal that engages downstream substrates such as SGK3." (PMID 28287465, 2017). "However, in other contexts, if KRAS and PIK3CA or EGFR and PIK3CA were tested, then testing for only two genes would be more expensive than the cancer panel." (PMID 28196074, 2017). "Autophagy inhibition augmented the efficacy of BKM120 depending on PIK3CA-mutant cancer cell type." (PMID 28036259, 2017). "However, their stage II carcinoma located in the rectum presented KRAS G12V and PIK3CA H1047R, two different mutations." (PMID 29069792, 2017). "Importantly, we report for the first time a significant correlation exists between the degree of interindividual variability in PIK3CA and KRAS MFs in normal tissues and the tissue‐specific prevalence of the mutations in carcinomas." (PMID 28755461, 2017). "Sequence variations outside of cancer “hot spots” (e.g., PIK3CA exon six) could reduce oncogenic function and thereby protect against malignancy in ASD patients." (PMID 26934580, 2016).
cancer (continued). "Inhibition of PI3K as a potential therapeutic approach in UC has not previously been examined, though mutations in PIK3CA represent the most frequent PI3K pathway mutations in this cancer type, including 12–20 % of muscle-invasive tumors." (PMID 27465249, 2016). "We reported that mutations in some cancer driver genes mutations in some cancer driver genes such as APC, KRAS, or PIK3CA might correlate with cancer proliferation or drug resistance." (PMID 26937901, 2016). "PIK3CA mutation-positive patients were at earlier cancer stage at initial diagnosis than PIK3CA mutation-negative patients." (PMID 27734950, 2016). "TKI resistance can arise through aberrant activation of the PI3K/AKT/mTOR axis in several cancer types, including NSCLC, often through PTEN deletion or activating PIK3CA mutations; however, such mechanisms were elucidated primarily in the context of EGFR inhibitors." (PMID 27472392, 2016). "AKT1 and AKT2 are frequently activated in human cancer following loss of the lipid phosphatase PTEN, activating mutations and/or copy number variation in EGFR or HER2 tyrosine kinase receptors, activating mutations in KRAS, in PIK3CA or in AKT1 itself." (PMID 26859676, 2016). "The PIK3CA gene is amplified in many cancers including head and neck, lung, gastric and cervix." (PMID 27489350, 2016). "Because of the rarity of PIK3CA mutation, its prognostic value with regard to carcinomas has not been thoroughly examined in previous studies." (PMID 27554588, 2016). "Finally, PIK3CA/AKT/mTOR signaling is ubiquitously deregulated in cancer, and it is apparent that there is significant crosstalk between this pathway and that related to androgens." (PMID 25595907, 2015). "In this study, we showed that clinically achievable concentrations of aspirin and ABT-737 in combination could induce a synergistic growth arrest in several human PIK3CA wild-type cancer cells." (PMID 25388762, 2015). "We also identified a number of ‘cancer genes'18 as significantly mutated in PDA, including BCLAF1 (5% of cases), IRF6 (4% of cases), FLG (10% of cases), AXIN1 (5% of cases), GLI3 (6% of cases) and PIK3CA (4% of cases)." (PMID 25855536, 2015). "We developed a novel mass spectrometry multiplexed genotyping platform named PentaPanel to concurrently assess single nucleotide polymorphisms in 56 hotspots of the 5 most clinically relevant cancer genes, KRAS, NRAS, BRAF, EGFR and PIK3CA for a total of 221 detectable mutations." (PMID 26435479, 2015). "In addition, Pc1Pik3caH1047R mice, which contain the most common alteration in the PIK3CA gene in human cancers, were also shown to develop metaplasia, PanINs, and invasive cancer." (PMID 26436951, 2015).
cancer (continued). "Moreover, we re-sequenced five exons from three frequently-mutated cancer genes, AKT1, PIK3CA, and BRAF, in an additional 120 ESCC samples." (PMID 26386145, 2015). "Although an increased cancer risk cannot be ruled out in patients with somatic PIK3CA mutations, data are currently very limited." (PMID 25915946, 2015). "The second identified genomic variation does not affect the amino acid sequence and is less frequent in cancer patients, with a frequency of 0.3% PIK3CA mutations reported in the COSMIC database." (PMID 24932282, 2014). "PIK3CA (phosphatidylinositol-4,5-bisphosphate 3-kinase, catalytic subunit alpha), the catalytic p110-alpha subunit of PI3K, has been described to be commonly mutated in various cancer, including glioblastoma, gastric, breast, ovary, lung, and CRC." (PMID 24624362, 2014). "However, we observed an increased frequency of PIK3CA mutation in LST-G, compared with other types of CRNs, and four of these five lesions histologically revealed HGD or T1 cancer." (PMID 25093594, 2014). "However, no information is available from the literature regarding the status of BRAF or PIK3CA in this cancer type." (PMID 24642661, 2014). "Of interest, compared to KRAS-wild-type, overall, KRAS-mutated cancers more frequently exhibited cecal location (24% vs. 12% in KRAS-wild-type; P < 0.0001), CIMP-low (49% vs. 32% in KRAS-wild-type; P < 0.0001), and PIK3CA mutations (24% vs. 11% in KRAS-wild-type; P < 0.0001)." (PMID 24885062, 2014). "The overexpression of PIK3CA has been reported in various types of cancer including ESCC." (PMID 25054828, 2014). "Besides these commonly occurring ‘hotspot’ PIK3CAmutations, rarer PIK3CA mutations on the C2 and RBD domains have also beenfound in human cancers." (PMID 25192370, 2014). "Interestingly, all cell lines that were sensitive to SREBP ablation show mutations in a component of the PI3-kinase pathway (PTEN, PIK3CA or KRAS; COSMIC cancer cell line project), while the insensitive SKBR3 cell line is wild type for these genes." (PMID 24280005, 2013). "Recent in vitro studies showing increased sensitization of cancers with defects in DNA homologous recombination (as seen in BRCA1/2 deficient cancers), to PARP inhibition by targeting of PIK3CA suggest that PIK3CA/mTOR pathway interactions result in homologous recombination steady state." (PMID 23971979, 2013). "Gain-of-function mutations on PIK3CA gene encoding for p110α isoform have been detected in a wide variety of human cancers whereas no somatic mutations of genes encoding for p110β or p110δ have been reported." (PMID 23459844, 2013). "In addition, amplifications of AKT1 and AKT2, as well as of PIK3CA have been described in some cancers, but seem to play a subordinate role compared to the other described mechanisms." (PMID 24036443, 2013). "MGMT methylation (38% vs. 28%) and MLH1 methylation (16% vs. 10%) were also more frequent in PIK3CA-mutated carcinomas compared with PIK3CA wild-type carcinomas, although neither reached statistical significance (P = 0.27 and P = 0.06, respectively)." (PMID 23785428, 2013). "Several NSCLCs analysed in this study over-expressed PIK3CA, implying that the deregulated expression of wild type p110α might represent an oncogenic event during cancer development in the lung." (PMID 22363436, 2012). "However, growth of all 6 cell lines was compromised by complete withdrawal of glucose even in the presence of glutamine, supporting the concept that PIK3CA mutant cancers are heavily reliant on glucose to support cell growth." (PMID 23028762, 2012). "PIK3CA mutations have been associated with paclitaxel resistance in breast epithelial cells and the PI3K/Akt pathway has been linked with resistance to a number of other cancer therapies." (PMID 22949056, 2012).
cancer (continued). "In contrast to all the common oncogenic genetic alterations that are associated with high cancer risk, this SNP was associated with a significantly reduced risk of development of FTC and PIK3CA amplification, adding a novel dimension to the genetic arrays in thyroid tumorigenesis." (PMID 23185308, 2012). "Thirdly, the increase in PIK3CA copy number or the presence of activated PI3KCA following mutations, much more prevalent in ATC than in differentiated carcinomas, could also reflect a progression in the cancer phenotype." (PMID 23115614, 2012). "An association between PIK3CA and RAS or BRAF mutations has implications for cancer therapy." (PMID 21829508, 2011). "Of the genes which encode the enzymatic subunit of PI3K heterodimers, the PIK3CA gene, encoding the p110∝ protein, has been found to be most frequently, in not exclusively, mutationally activated in some human cancers." (PMID 21473780, 2011). "Several small molecule inhibitors of PIK3CA are in anti-cancer clinical trials." (PMID 21208444, 2011). "Genetic aberrations of PIK3CA, located on chromosome 3, are also commonly found in human cancer." (PMID 21317449, 2010). "We demonstrate that RNAi screens can be used to identify genes that are differentially required for viability of cancer cell lines and, as proof of this principle, identify the known oncogene PIK3CA as essential for viability in MCF7 cells with an activating PIK3CA mutation." (PMID 19357772, 2009). "Besides mutations in RAS, activating somatic mutations in its effectors PIK3CA and BRAF, occur in various human cancers." (PMID 19492075, 2009). "Consistent with this hypothesis, the hypoxia/HIF pathway has been reported to regulate PIK3CA in cancer cells." (PMID 18335034, 2008). "The frequency of PIK3CA mutations was similar in patients with extremely chemotherapy-sensitive tumors indicated by pCR and those with lesser response (RCB-I or RCB-II) or even with extensive residual cancer (RCB-III)." (PMID 18371219, 2008). "Moreover, the PIK3CA gene, encoding the catalytic p110α isoform of PI3K is mutated in a variety of human cancers." (PMID 18949068, 2007). "Recently, the Ras effector PIK3CA was shown to be activated in diverse human cancers." (PMID 16822308, 2006). "Both amplification/gain of gene copy number and somatic mutation of PIK3CA have been shown to be associated with increased PI3K activity and might contribute to cancer through inhibition of apoptosis." (PMID 16168105, 2005). "In addition, we analyzed PIK3CA expression in pan-cancer using TIMER 2.0." (PMID 40332095, 2025). "Thus, inhibition/silencing of PI3K, Akt, mTORC1, SREBP1, or SCD1 sensitizes (cancer) cells to ferroptosis and activating mutations in PIK3CA, which encodes for the catalytic subunit of PI3K, cause ferroptosis resistance in cancer cells via the SREBP1-SCD1-axis." (PMID 40000627, 2025). "Consistent with reports on the prevalence and clinical implications of PIK3CA aberrations across cancer types and the emerging role of PTEN alterations in NSCLC biology, these variants help refine prognostic expectations and may signal mechanisms of resistance to other therapies." (PMID 41465119, 2025). "Identifying patients who may benefit from capivasertib after progression on first-line ET (i.e., those whose cancer has ≥1 PIK3CA, AKT1, and/or PTEN alterations), will provide an opportunity to achieve glycemic control, if needed, before initiating capivasertib." (PMID 41345397, 2025). "For example, the PIK3CA mutation c.3140A>G (p.His1047Arg) identified in this study is one of the most frequently reported mutations in endometrial cancer and has been extensively documented as a driver of the PI3K/AKT pathway, contributing to tumorigenesis and cancer progression." (PMID 39296440, 2024).
cancer (continued). "Furthermore, despite thorough sequencing studies, no significant point mutations, whether germline or somatic, were identified in frequently mutated cancer-associated genes such as KRAS, BRAF, and PIK3CA, concerning SFT." (PMID 39364485, 2024). "This highly conserved structural feature of SH2 domains allows interpretation of the molecular mechanism for why the cancer hotspot variants (p.E542K and p.E545K) are seen with high recurrence—they are precisely the residues that determine specificity between the receptor SH2 domain and PIK3CA." (PMID 38541623, 2024). "The PIK3CA gene (the phosphatidylinositol-4,5bisphosphate 3-kinase catalytic subunit alpha gene) is the most frequently altered PI3K isoform in solid tumors, with gain-of-function mutations upregulating downstream AKT-mTOR signaling pathways that promote cancer cell growth and proliferation." (PMID 39070139, 2024). "In Case 3, a CDK12 variant was detected in all cells of Regions A and B; whereas, four variants in ATRX, BRCA2, PIK3CA, and PPARG were detected specifically in Region A. All four variants displayed low VAFs (0.05–0.07), indicating a late molecular event present in a small subset of cancer cells." (PMID 39766052, 2024). "Right-sided cancers are associated with higher rates of microsatellite instability (MSI), more frequent aberrant activation of the EGFR pathway including higher BRAF and PIK3CA mutation rates, and increased mutational burden compared to cancers in other locations." (PMID 38062443, 2023). "The most recent results of an ongoing phase I clinical trial (NCT02861300) on CB-839 with Capecitabine (a 5-FU prodrug) for advanced CRC and other solid tumors yielded a better therapeutic outcome for patients with mutated PIK3CA than those with non-mutated cancers." (PMID 36959802, 2023). "Considering that the ERBB family member ERBB3 was reported to recruit PI3Kβ and thereby drive PI3Kα inhibitor resistance in HER2‐amplified and PIK3CA mutant cancers, we hypothesized that ALK inhibition may similarly activate EGFR and thereby regulate PI3Kβ function." (PMID 36423211, 2023). "In contrast, patients without PIK3CA-mutated cancer did not benefit from alpelisib treatment." (PMID 35780223, 2022). "Gene mutations in PIK3CA, PIK3R1, and PTEN are commonly detected in type I EC and may lead to activation of the PI3K/Akt/mTOR pathway, which is central to cell growth and proliferation in cancer." (PMID 35902869, 2022). "Moreover, our data suggest that targeting both pathways with Alpelisib and Tazemetostat could be an effective therapeutic approach for PIK3CA helical domain mutant cancers." (PMID 35418124, 2022). "Moreover, BRAF mutated cancers with and without PIK3CA mutations are characterized by the absence of KRAS mutations and a lower prevalence of APC mutations than BRAF wild type counterparts." (PMID 36079062, 2022). "Consequently, it is possible that a WT PIK3CA cancer may recur despite an effective T cell response targeting the PIK3CA public NeoAg." (PMID 35484264, 2022).